OR10A6 (olfactory receptor family 10 subfamily A member 6 (gene/pseudogene))
Description:
Odorant receptor.
Synonyms: OR11-96
Tractability: Antibody: its Gene Ontology location is reachable by antibodies, with high confidence; UniProt places it where antibodies can reach, with medium confidence; UniProt predicts a signal peptide or a membrane-spanning region.
Gene: Protein-coding gene on chromosome 11 (7,924,592 to 7,931,268, reverse strand). Ensembl gene ENSG00000279000.
Subcellular location: Cell membrane
Pathways (Reactome):
Sensory Perception: Expression and translocation of olfactory receptors; Olfactory Signaling Pathway
Gene Ontology:
Molecular function: olfactory receptor activity; G protein-coupled receptor activity
Biological process: detection of chemical stimulus involved in sensory perception of smell; G protein-coupled receptor signaling pathway
Cellular component: plasma membrane; membrane
Genetic constraint (gnomAD): Loss-of-function variants: 5 observed, 7.33 expected, observed/expected ratio (o/e) 0.68, 90% interval 0.35 to 1.42. That is too few expected variants to judge how well the gene tolerates losing a copy. Missense variants: 484 observed, 382.62 expected, observed/expected ratio (o/e) 1.26, 90% interval 1.17 to 1.36. Synonymous variants: 166 observed, 142.97 expected, observed/expected ratio (o/e) 1.16, 90% interval 1.02 to 1.32.
Homologues: Orthologues: chimpanzee OR10A6 (98% identical), macaque OR10A6 (95% identical), dog OR10A3E (82% identical), dog OR10A3 (82% identical). Paralogues in human: OR10A3 (85% identical), OR10A5 (55% identical), OR10A2 (52% identical), OR10A4 (52% identical), OR10A7 (51% identical), OR10C1 (48% identical), OR13C4 (46% identical), OR2F2 (46% identical), OR2D2 (45% identical), OR2D3 (45% identical), OR10D3 (45% identical), OR2F1 (45% identical), and 80 more.
Diseases named in the same sentence as OR10A6 in open-access papers:
OR10A6 is named in the same sentence as 1 disease in open-access papers, as found by Europe PMC text mining. Sharing a sentence is not in itself a finding about the gene and the disease. The quoted sentences say what the papers report.
glaucoma (1 paper, 2023). Increased pressure in the eyeball due to obstruction of the outflow of aqueous humor. "Of most significant coding variants identified from exome sequencing by PDC80 following Bonferroni correction, SNPs rs9613558 (TTC28), rs7131178 (KIAA1731), and rs4758258 (OR10A6) were all found to be associated with protection or lower risk of glaucoma medication non-adherence." (PMID 36982708, 2023).